CXCR4 (C-X-C motif chemokine receptor 4)
Diseases named in the same sentence as CXCR4 in open-access papers (continued):
Sharing a sentence is not in itself a finding about the gene and the disease.
lung carcinoma (continued). "If CXCR4 truly mediates metastasis, when lung cancer cells enter the blood or lymphatic systems, they would preferentially migrate and adhere to areas with high expression of CXCL12." (PMID 23322021, 2013). "Most importantly, in samples with evaluable adjacent brain tissue, we discovered CXCR4 expression in the gliosis region next to the metastatic tissue in 80% of breast and 68.8% of lung cancer cerebral metastasis." (PMID 23832647, 2013). "Although there has been limited research on the signal transduction pathways mediated by CXCR4 in lung cancer cells, some of the mechanisms involved in NSCLC metastasis are beginning to be elucidated." (PMID 23322021, 2013). "Although these findings are very encouraging, additional studies are still necessary to test the safety and efficacy of CXCR4 inhibitors against lung cancer brain metastasis." (PMID 23322021, 2013). "Perhaps most interestingly, BRMS1 was shown to reduce CXCR4 expression via abrogation of NF-κB signaling, which led to metastasis suppression in lung cancer cells." (PMID 22200669, 2012). "However, although there are promising preclinical and encouraging early clinical data, it is important to address several issues before CXCR4-targeted therapies can become an integral part of lung cancer treatment." (PMID 41383468, 2025). "There is a limited collection of trials involving CXCR4 antagonists in lung cancer." (PMID 41383468, 2025). "For the step-wise metastatic mechanism driven by CXCR4/CXCL12 in lung cancer, see Section 2.1." (PMID 41383468, 2025). "Therefore, a growing interest in the therapeutic and biomarker utility of CXCR4 for patient selection in lung cancer is motivated by the strong evidence that implicates it in lung cancer progression and therapy resistance." (PMID 41383468, 2025). "Several clinical studies have further validated CXCR4 as a biomarker for lung cancer prognosis." (PMID 41383468, 2025). "Additionally, CXCL12/CXCR4 is believed to be involved in angiogenesis in lung cancer, and high expression of CXCR4 has been significantly associated with bone metastasis." (PMID 38711158, 2024). "Furthermore, the expression level of CXCL12 receptor CXCR4 in lung cancer cell was detected, and we found that iCAFs elevated CXCR4 level." (PMID 39759028, 2024). "A group of CD66b+/CD10low/CXCR4+/PDL1inter neutrophils were identified in the peripheral blood of advanced lung cancer patients, the existence of which was limited in the advanced stage of lung cancer." (PMID 37492784, 2023). "In addition, CXCR4 overexpression promotes cancer cell survival and metastasis, resulting in poor prognosis in patients with lung cancer." (PMID 38004606, 2023). "Inhibiting CXCL12/CXCR4 axis by CXCR4 antagonists can be a value treatment option in lung cancer." (PMID 35729596, 2022). "High expression of CXCR4 is related to tumor progression and might be an adverse prognostic factor for lung cancer." (PMID 35729596, 2022). "Our results showed that both JUNB and CXCR4 were overexpressed in CTCs from lung cancer patients." (PMID 36612166, 2022). "However, the applications of CXCR4 antagonists in lung cancer are relatively limited and need further exploration." (PMID 35729596, 2022). "In the present study, we evaluated the expression of JUNB and CXCR4 in circulating tumor cells (CTCs) of lung cancer patients and investigated whether these proteins have prognostic clinical relevance." (PMID 36612166, 2022). "For example, ESR2 (degree = 13), also known as ERβ, it could promote lung cancer invasion via increasing CXCR4 expression." (PMID 36339610, 2022). "Thus, we conducted a meta-analysis to investigate the impact of CXCR4 expression on survival and clinicopathological features in lung cancer." (PMID 35729596, 2022). "Both JUNB and CXCR4 were expressed in the vast majority of lung cancer patients." (PMID 36612166, 2022).
lung carcinoma (continued). "Finally, several genes, such as ADRA2A, P2RY12, ADORA1, CXCR1, and CXCR4, were predicted as potential druggable genes for ALI with GGPPS1-knockout, and were associated with the prognosis of lung cancers." (PMID 35795000, 2022). "In addition, a recent study involving tumors from NSCLC patients and lung cancer cell lines found that inhibiting CXCR4 with peptide R significantly reduced the dissemination of metastasis-initiating cells and their immunosuppressive tendencies." (PMID 36164329, 2022). "Thus, more research involving other populations is needed to further confirm the value of CXCR4 expression in lung cancer." (PMID 35729596, 2022). "As multivariate analysis is an effective method for reducing bias from various confounding variables and making statistically reliable conclusions, we reasoned that CXCR4 overexpression might be an independent prognostic factor in lung cancer." (PMID 35729596, 2022). "Overall, we hypothesized that CXCR4 inhibitors could improve the prognosis of patients with lung cancer by preventing the distal metastasis of tumor cells and improving the therapeutic effect of conventional therapy or immunotherapy." (PMID 35729596, 2022). "CXCR4 is involved in homeostasis through leukocyte trafficking and regulation of hematopoiesis, but also participates in cancer progression and metastasis in several neoplasms, including lung cancer." (PMID 36612166, 2022). "Studies have shown that JUNB and CXCR4 contribute to cell proliferation, migration and invasion, hence claiming an important role in tumor progression and metastasis, in various cancer types, including lung cancer." (PMID 36612166, 2022). "Our meta-analysis suggested that high CXCR4 expression could serve as a promising predictive marker for poor prognosis in lung cancer." (PMID 35729596, 2022). "Moreover, we found that CXCR4 upregulation was a prognostic factor for unfavorable OS in both early resected and metastatic patients with lung cancer." (PMID 35729596, 2022). "Although the number of patients in this manuscript is relatively small, it provides the basis for the importance of JUNB and CXCR4 expression in lung cancer patients’ CTCs as an indication of patients’ poor survival and further supports their role in metastasis, confirming related studies." (PMID 36612166, 2022). "CXCR4 antagonists combined with conventional therapy or immunotherapy may enhance the treatment efficacy and improve the prognosis of patients with lung cancer." (PMID 35729596, 2022). "Moreover, to better comprehend the key role of CXCR4 modulation in lung cancer dissemination, CXCR4 expression was silenced with a commercially available siRNA (si‐CXCR4), and alterations in the migratory and invasive capacities were examined." (PMID 34107168, 2021). "In summary, we showed that SDF-1 secreted by CAF might act via the CXCR4/β-catenin/PPARδ signalling pathway to regulate lung cancer EMT." (PMID 33637678, 2021). "Interestingly, the estrogen receptor α promotes cancer cell invasion via the increase of and cross-talk with infiltrated macrophages through the CCL2/CCR2/MMP9 and CXCL12/CXCR4 signaling pathways at least in lung cancer." (PMID 34833360, 2021). "There might be a crucial function for SDF-1/CXCR4 in promoting chemotaxis lung cancer cells gather to the brain astrocytes and secreting lysozyme to damage BBB." (PMID 34531745, 2021). "Furthermore, expression levels of CXCR4 tended to be positively correlated with integrin αvβ3 levels in lung cancer specimens (r = 0.22, p > 0.05)." (PMID 34121134, 2021). "CXCR4 and integrin might synergistically promote lymphatic metastasis in lung cancer, and act as clinical predictors of lymph node metastasis in non-SCLC." (PMID 34121134, 2021). "Indeed, simultaneous miR‐126 replacement and miR‐221 inhibition reduced the migratory and invasive capacities of lung cancer cells through blockade of the CXCR4 axis." (PMID 34107168, 2021).
lung carcinoma (continued). "A cyclic peptide inhibitor of CXCR4 (peptide R), designed as an SDF‐1 mimetic peptide, and already validated to inhibit CXCR4 downstream pathways and to exert anti‐metastatic effects, was utilized to better explain the role of CXCR4 inhibition in the modulation of lung cancer metastatic potential." (PMID 34107168, 2021). "Firstly, we are limited by the retrospective nature of the analysis; however, our data collection was comprehensive and included a substantial number of early stage patients in comparison to other published studies evaluating CXCR4 expression in lung cancer patients." (PMID 33507926, 2021). "Interestingly, miR‐126‐3p replacement reduced lung cancer metastatic dissemination through CXCR4 blockade both in vitro and in vivo." (PMID 34107168, 2021). "Therefore, it is essential to produce adequate evidence on the therapeutic role of CXCL12/CXCR4 in lung cancer and bone metastasis." (PMID 34722241, 2021). "CXCR4 was highly expressed in lung cancer, as demonstrated by IHC." (PMID 34121134, 2021). "While exact mechanisms for preferential metastasis of lung cancer to bone are unclear, recent data implicate growth factors including TGF-beta, cytokines and chemokines such as stromal-derived factor-1 (SDF-1) and CXCR4, and matrix metalloproteinases that help drive lung cancer metastases to bone." (PMID 33572757, 2021). "CXCR4 expression is high in primary and metastatic lung cancers." (PMID 32260318, 2020). "Furthermore, ERα‐increased macrophage infiltration can induce a positive feedback mechanism to increase lung cancer cell ERα expression via the up‐regulation of the CXCL12/CXCR4 pathway." (PMID 32356397, 2020). "CXCR4 has been also proposed as a relevant target in lung cancers." (PMID 32224910, 2020). "Furthermore, our results showed that CXCR4 was significantly upregulated when circFGFR1 was overexpressed in LLC mouse lung cancer cells." (PMID 31815619, 2019). "Recently, combined HuR and CXCR4 targeting effectively controls lung cancer metastasis." (PMID 30787392, 2019). "Furthermore, the challenges and potential benefits of incorporating drugs that target CXCL12/CXCR4 into immune-based lung cancer therapeutic protocols are discussed." (PMID 30257500, 2018). "The researchers found that individuals with the CXCL12 AA (high expressing genotype) and CXCR4 TT genotypes had higher odds ratios (an OR of 1.95, 95% CI 1.08–3.50, p = 0.018 and OR of 4.71, 95% CI 1.99–11.2, p < 0.0001, respectively) for lung cancer development." (PMID 30257500, 2018). "Interestingly, it has been recently shown that inhibition of FAK and CXCR4 and simultaneous treatment of lung carcinoma cells with doxorubicin potentiated their anti-tumorigenic effects." (PMID 28953264, 2017). "One meta-analysis of the relationship between CXCR4 expression and lung cancer indicates that elevated CXCR4 expression is correlated with aggressive metastasis, advanced TNM stages, and shorter overall survival in NSCLC patients, suggesting a poor prognostic outcome of this disease." (PMID 28903328, 2017). "However, overexpression of CXCR4 has been shown to lead to metastasis of breast and lung cancer cells." (PMID 27812115, 2016). "Notably, a number of GPCRs, including CXCR4, CXCR2 and EP receptors, have been implicated in the organ-specific metastasis of lung cancer." (PMID 26760963, 2016). "Apart from measuring the IL-24 inhibitory effect on cell migration and invasion, we also investigated whether the AKT/mTOR signaling pathway that is downstream of SDF-1/CXCR4 axis and essential for lung cancer progression and metastasis was also affected." (PMID 25775124, 2015). "The contribution of the SDF-1/CXCR4 axis to lung cancer development and metastasis identified in this study is consistent with previous reports by others, in which the SDF-1/CXCR4 axis was found to be associated with lung cancer metastasis as well as patient survival." (PMID 26416452, 2015).
lung carcinoma (continued). "In the present study we investigated whether interleukin (IL)-24 can inhibit the SDF-1/CXCR4 axis and suppress lung cancer cell migration and invasion in vitro." (PMID 25775124, 2015). "Endogenous CXCR4 protein expression levels varied among the four human lung cancer cell lines." (PMID 25775124, 2015). "Thus, combining IL-24 with CXCR4 inhibitors is an attractive therapeutic strategy for controlling lung cancer metastasis." (PMID 25775124, 2015). "TLR9 agonist could enhance the metastatic potential of human lung cancer 95D cells via CXCR4/SDF-1(chemokine receptor 4/chemokine ligand 12) pathway." (PMID 26087186, 2015). "Indeed, in preclinical studies, it was demonstrated that neutralization of SDF-1 by an anti-SDF-1 or anti-CXCR4 monoclonal antibody resulted in a significant decrease of lung cancer metastases." (PMID 26416452, 2015). "Thus, membrane CXCR6 and CXCR4 were coexpressed in three lung cancer cell lines despite of a slight difference in the positive expression proportion." (PMID 24897301, 2014). "Expression intensity of CXCL16/CXCR6 and CXCL12/CXCR4 protein in human lung cancer tissues." (PMID 24897301, 2014). "In conclusion, the results of the current study indicate that CXCR4 siRNA treatment may significantly inhibit the growth, invasion and metastasis of lung cancer cells." (PMID 24944647, 2014). "Different factors can also influence CXCL12 and CXCR4 expression in lung cancer." (PMID 23322021, 2013). "To date, studies have shown that HIF-2α, TWIST, and CXCR4 are overexpressed in several human tumors such as clear cell renal carcinoma (ccRCC), nonsmall cell lung cancer (NSCLC), neuroblastoma, and breast, prostate, gastric, hepatocellular, colon, and bladder cancers." (PMID 24288553, 2013). "Therefore, targeting PLAU and CXCR4 expression with natural compounds should result in the suppression of breast to lung cancer metastasis." (PMID 22842551, 2012). "Indeed, here we show that 70% of the inhibition of breast-to-lung cancer metastases is associated with the downregulation of expression of PLAU and CXCR4 in primary tumors in mice treated with BD." (PMID 22842551, 2012). "Moreover, PLAU and CXCR4 expression in primary tumors was significantly increased in animals with breast-to-lung cancer metastasis." (PMID 22842551, 2012). "Moreover, the relative expression of PLAU and CXCR4 in primary tumors is a predictive marker of breast-to-lung cancer metastasis because we have identified significant increase of these genes in animals with metastases." (PMID 22842551, 2012). "CXCR7 is a recently described second receptor for CXCL12 and was shown to promote lung cancer growth in vivo but this receptor might rather modulate CXCR4-mediated responses than act as an independent CXCL12 receptor." (PMID 19455144, 2009). "However, in lung cancer, CXCR4 overexpression facilitates tumor cells to migrate along chemotactic gradients of its ligand CXCL12 (stromal cell-derived factor 1, SDF-1) toward CXCL12-enriched metastatic niches, where tumor adhesion, survival, and immune escape are enhanced." (PMID 41383468, 2025). "Similarly, in lung cancer, elevated epidermal growth factor receptor (EGFR) expression has been tentatively linked to CXCR4 induction, correlating with poor clinical outcomes; however, further mechanistic validation is required to establish this relationship conclusively." (PMID 40607416, 2025). "Furthermore, the CXCR4 antagonists suppressed the growth of lung cancer growth: Peptide R prevented the recruitment of metastasis-initiating cells and inflammatory monocytes toward CXCL12-enriched sites and AMD3100 reduced the progression of cancer in orthotopic SCLC mouse model." (PMID 39114657, 2024). "Therefore, targeting the CAF-derived SDF-1-mediated CXCR4/β-catenin cascade may be an effective approach for lung cancer treatment." (PMID 36901697, 2023). "However, the clinical significance and application of CXCR4 in lung cancer remain disputable." (PMID 35729596, 2022).
lung carcinoma (continued). "The heterogenous CXCR4 expression shown in these studies shows that CXCR4-targeted imaging cannot replace 18F-FDG in lung cancer; however, CXCR4-targeted imaging with 68Ga-Pentixafor can be used to select patients who may benefit from these therapies and to monitor treatment response." (PMID 36140541, 2022). "Analysis of PD-L1 and CXCR4 could hence be informative in the future in lung cancer patients." (PMID 36612166, 2022). "Moreover, through the lentiviral transduction of two different shRNAs (shERα#1 and shERα#2) or the treatment with a selective ERα antagonist, we proved that the regulatory pathway is through the production of macrophage CXCL12 to activate its receptor, CXCR4, on lung cancer cells." (PMID 32356397, 2020). "However, the challenge of developing CXCR4 therapeutics for lung cancer remains highly complex." (PMID 30257500, 2018). "AMD3100 (plerixafor), a selective CXCR4 antagonist and disrupts the CXCR4/CXCL12 signaling and has shown antitumor activity in preclinical lung cancer models." (PMID 41383468, 2025). "Because CXCR4/CXCL12 constitutes a powerful therapeutic target to counter tumor progression, immune evasion, and therapy resistance, it plays a pivotal role in lung cancer." (PMID 41383468, 2025). "Recognizing the critical role of SDF‐1/CXCR4 axis, our laboratory conducted studies to examine the impact of IL‐24 overexpression on key target molecules in the SDF‐1/CXCR4 pathway in lung cancer models." (PMID 40338095, 2025). "Compared with PBNs in lung carcinomas patients, increased levels of CCR5, CCR7, CXCR3, and CXCR4 are expressed in TANs, whereas CXCR1 and CXCR2 expression are downregulated." (PMID 41254689, 2025). "The presence of JUNB and/or CXCR4‐positive CTCs correlated with shorter overall survival (OS) and progression‐free survival (PFS) in metastatic breast and lung cancer patients." (PMID 39575761, 2025). "Interaction between cancerous cells, stromal components, and immune cells in the lung cancer TME requires the key regulator of this process, CXCR4." (PMID 41383468, 2025). "CXCL12 acts through the C-X-C motif receptor 4 (CXCR4) to promote the recruitment of CXCR4+ neutrophils and leukocytes to the TME as well as to facilitate metastasis of lung cancer." (PMID 40589738, 2025). "Researchers proved that the simultaneous interaction of these molecules reduced metastatic dissemination of lung cancer cells both in vitro and in vivo through CXCR4 (C-X-C Motif Chemokine Receptor 4) inhibition." (PMID 38469304, 2024). "Flow cytometric analysis of PBMC from 18 patients with lung cancer on samples collected immediately before the first and the second treatment was performed to study Lin-CD34+DNAM-1bright CXCR4+ precursors." (PMID 38390333, 2024). "Overall, CXCR2, CXCR4, CCR2 are currently the most extensively studied chemokine receptors in NSCLC and are considered potential biomarkers for lung cancer." (PMID 39114657, 2024). "In non-small cell lung cancer, in vitro experiments demonstrate that CXCL12 binding to CXCR4, via activation of the JAK2/STAT3 signaling pathway, reduces the proportion of lung cancer cell apoptosis induced by the chemotherapeutic drug cisplatin." (PMID 38920657, 2024). "SDF4 interacts with CXCR4 to trigger VEGFD expression in endothelial cells and promotes the angiogenesis of lung cancer." (PMID 36606322, 2023). "The CXCR4/CXCL12 axis has been extensively studied and shown to promote cancer cell migration, invasion, and metastasis in a variety of cancers, such as lung cancer, liver cancer, breast cancer, prostate cancer, and esophageal cancer." (PMID 36308553, 2023). "CAFs isolated from lung cancer promoted EMT via stromal cell-derived factor-1 (SDF-1), thereby upregulating CXCR4 and β-catenin." (PMID 36901697, 2023). "Lung cancer cells can affect the TME by expressing chemokine receptors, majorly CXCR4, and producing chemokines that regulate the transportation of immune and cancer cells." (PMID 36308553, 2023).